IFNG (interferon gamma)
Diseases named in the same sentence as IFNG in open-access papers (continued):
Sharing a sentence is not in itself a finding about the gene and the disease.
tumor (continued). "R848@M2pep-MPsAFP treatment also significantly increased the numbers of the activated CD8+CD69+ T cells, CD8+IFNγ+ T cells and CD8+GzmB+ T cells in spleens of orthotopic Hepa1-6 tumor-bearing mice, suggesting that R848@M2pep-MPsAFP efficiently activated the systemic antitumor immunity." (PMID 37704614, 2023). "To address this, we performed a de novo unsupervised clustering analysis between the four features with a multiple correspondence analysis (MCA) using categorical values from CD8+ T cell sub-populations, IFNG expression, predicted TCR antigen-groups, and tumor-reactive signaling modules." (PMID 37968259, 2023). "Specifically, interferon-gamma (IFN-γ) and its induced production of CXCL9 and CXCL10 contribute to the establishment of an inflammatory tumor microenvironment, which plays a role in the tumor’s response to ICIs therapy." (PMID 37835371, 2023). "Interferon gamma, produced in T cells, in particular, plays a central role in the expression of antitumor activity, and is also a major driving force in the induction of PD-L1 and MHC class I expression in tumor cells." (PMID 36765886, 2023). "Furthermore, the over stimulation with IFNγ ultimately led to the downregulation of IFNγ receptors, CD8 + T cell downregulation, and tumor relapse." (PMID 36854896, 2023). "Moreover, pro-inflammatory mediators such as IFNγ, IL-1β, and IL-6 also induce EMT-TFs, leading to chronic inflammation in the tumor microenvironment, immune escape, and the acquisition of EMT-like features in tumor cells." (PMID 37370762, 2023). "Notably, Cluster 1, 2, and 4 showed better response to ICIs, which should be due to TME supporting anti-tumor immunity, including IL6/JAK/STAT3 signaling, tumor necrosis factor (TNFA, TGFB) and interferon (IFNA, IFNG) pathways." (PMID 36817452, 2023). "A series of inflammatory cytokines, such as Interferon-gamma (IFN-γ), secreted by activated T-cells and NK cells, can promote PD-L1 expression in a variety of cell types, including epithelial, endothelial, hematopoietic, and tumor cells." (PMID 36931099, 2023). "Besides, IFNG was also a key mediator of antitumor immunity with angiostatic activity, mediated the effects of anti-CTLA4 therapy on vessel perfusion and tumor growth." (PMID 36756126, 2023). "To get further insight into relationship with cell states during proliferation, we isolated all tumor-infiltrating immune cells from WT mice, treated those with anti-CD3 and anti-CD28, and assessed how IFNγ sensing affected stem-like and exhausted T cells proportion ex vivo." (PMID 36658158, 2023). "We have also developed anti-IFNγ nanoparticles coated with a clot-binding peptide CREKA (CREKA-lipo-anti-IFNγ), which targets the fibrin-fibronectin complex that appears in the leaky site of damaged tumour blood vessels." (PMID 37056922, 2023). "M1 macrophages sustain themselves as well as induce NK cell and cytotoxic T-cell infiltration and activation in the tumor site by secreting substantial amounts of pro-inflammatory cytokines IFNγ and IL12 with anti-tumor activity, indicating an indirect mechanism of inhibiting cancer progression." (PMID 38035101, 2023). "R848@M2pep-MPsAFP significantly increased the numbers of CD4+ T cells, activated CD4+CD69+ T cells, CD8+ T cells, proliferated CD8+ T cells and activated CD8+CD69+ T cells, CD8+IFNγ+ T cells and CD8+GzmB+ T cells in tumor tissues compared with free R848, R848@MPs, R848@M2pep-MPs and R848@MPsAFP." (PMID 37704614, 2023). "It was found that certain gut microbiota enhanced the expression of major histocompatibility complex (MHC) class I in DC, followed by activation of interferon gamma (IFN-γ)+CD8+ T cells, and increased the number of (IFN-γ)+CD8+ tumor-infiltrating lymphocytes in the TME to inhibit the growth of CRC." (PMID 36950522, 2023).
tumor (continued). "The authors also showed that GL261-bearing mice deficient in miR-15a/16 had lower expression of PD1, TIM3 and LAG3 and displayed higher production of IFNγ, IL2 and TNFα, which relieved the immunosuppressive state of CD8+ T cells, reduced the tumor volume and prolonged mice survival." (PMID 37274252, 2023). "In general, we found that TAG72-CAR T cells containing the dCH2 spacer domain showed superior functionality with the greatest tumor cell killing, highest CD137 activation, enhanced antigen-dependent T-cell proliferation, and robust IFNγ and IL-2 cytokine production." (PMID 37550294, 2023). "Interferon-gamma (IFN-γ) is a pro-inflammatory cytokine produced mainly by T cells and NK cells, among others, and plays an important role in regulating intrinsic and acquired immune responses in the tumor microenvironment." (PMID 37513021, 2023). "Although interferon-γ (IFNγ) was essential for establishment and maintenance of equilibrium, tumor or host sensing of IFNγ was redundant and tumors were controlled without direct T cell cytotoxicity." (PMID 36881506, 2023). "Based on the importance of IFNγ in establishing and maintaining stable tumor control in response to d106S-IL12 therapy, we hypothesized that large amounts of IFNγ could act directly on the tumor and slow its growth." (PMID 36881506, 2023). "Together, these data suggest that in a tumor model that does not experience IFNγ induction from VV alone, combining with another immunostimulatory therapy such as αPD-1 can lead to the fragility of Treg cells and increase effector function." (PMID 37552475, 2023). "TPI-1 treatment enhances the number of IFNγ+ cells in mouse and human immune cells and slows tumor growth in immunocompetent mice, but not in athymic nude mice." (PMID 38022587, 2023). "This study provides evidence of a negative feedback loop whereby IFNγ depletes stem-like T cells to restrict anti-tumor immunity." (PMID 36658158, 2023). "On the other hand, a hepatocarcinoma murine model demonstrated that tumor-infiltrating mast cells activated by tumor-derived stem cell factor (SCF) augment immunosuppression, and adenosine released by MCs suppresses NK cell activity with the reduction of interferon gamma release in TME." (PMID 37628724, 2023). "Aerobic glycolysis is required for IFNγ production in anti-tumor effector CD8+ T cells, but rapid consumption by tumor cells restricts the availability of glucose to T cells that dampens glycolysis and IFNγ production, leading to CD8+ T cell anergy or exhaustion." (PMID 36765614, 2023). "However, the expression of genes participating in AP (e.g., HLA‐DRA/DMB and CD74) and anti‐tumour immunity (e.g., GBP1, IFNG and TNFRSF9) were significantly higher in the TS, while genes involved in angiogenesis (e.g., VEGFA) was significantly higher in TN." (PMID 37491740, 2023). "Interestingly, prior studies showed that ERK signaling negatively regulates constitutive but also IFNγ-induced CIITA expression, suggesting that oncogenic Ras-RAF-MEK-ERK pathway activation in tumor cells counteracts MHC class II antigen presentation." (PMID 37965314, 2023). "Moreover, we found high levels of IFNG in the early stages of CRC, suggesting a higher anti-tumor activity of lymphocytes than in the late stages." (PMID 37228491, 2023). "While T cells transduced with the TCR from beads stimulated T-iPSC did not express 4-1BB nor produced IFNγ, those with the TCR from tumor cell-stimulated T-iPSC expressed 4-1BB and produced IFNγ as PIR-TCR." (PMID 37377887, 2023). "In this process, interferon-γ (IFNγ) derived from activated CD8+ T cells has been shown to defer the expression of SLC3A2 and SLC7A11, inhibiting tumor cell cystine import and sensitizing tumor cells to ferroptosis." (PMID 37840106, 2023).
tumor (continued). "Notably, the activated T cells secrete Interferon‐gamma (IFNγ), which in turn enhances GSDMB expression, thus establishing a positive feedback loop that augments T cell activation and facilitates efficient tumor cell elimination." (PMID 37587833, 2023). "Additionally, the same effects were observed in metastatic ovarian cancer models and were accompanied by the infiltration and accumulation of CD44+ IFNγ-secreting CD8+ and CD4+ T cells at tumour beds." (PMID 38136940, 2023). "In conclusion, we propose antagonism of PARP14 with a catalytic inhibitor as a safe and efficacious approach to target high tumour cell intrinsic IFNγ signalling resulting from adaptation to α-PD-1 and thereby restore sensitivity to ICBT in progressing tumours." (PMID 37752135, 2023). "Coculture of TR 29.ct2 transgenic T cells with the tumor cells resulted in a very strong release of IFNγ, while no relevant IFNγ production was observed without tumor cells." (PMID 38077312, 2023). "In addition, Lactobacillus delays tumor initiation by increasing infiltration of NK cells, CD8+ T cells and production of IFNg in cancer microenvironme." (PMID 37143538, 2023). "IFNγ receptor genes IFNGR1, IFNGR2 and the downstream effector IRF1 have been reported to be expressed on a PNET cell line QGP-1, and IFNγ treatment could inhibit tumor growth and induce apoptosis in vitro, indicating a direct anti-PNET effect of IFNγ." (PMID 38020179, 2023). "The in vivo anti-tumor efficacy of adoptively transferred murine TCR transgenic T cells was improved by Snx9 KO, which correlated with increased effector-memory-like differentiation, enhanced chemokine expression, and elevated IFNγ serum levels." (PMID 36732507, 2023). "Among the recognized cytokines that play crucial roles in anti-tumor immunity are IFN-gamma (IFNG) and type I IFN, enhancing infiltrating CD8 + T cell-produced IFN-γ can boost tumor immunity, which in turn can trigger tumor retreat, by recruiting inflammatory cells to the tumor microenvironment." (PMID 37777634, 2023). "The deletion of PTPN2 in T cells not only promoted the activation and cytotoxic potential of tumor-infiltrating/resident T cells (as reflected by IFNγ, TNF and GZMB levels), but also enhanced STAT-1 signaling in AT3-OVA tumor cells, the expression of Cxcl9 and the recruitment of T cells." (PMID 37500611, 2023). "The data confirm that IFNγΔKRKR has retained biological activity and that ECM binding of IFNγ is not necessary for tumor rejection in vivo." (PMID 36732425, 2023). "Consistent with α-PD-1 not inducing PARP14 in responding tumours, PARP14i treatment failed to inhibit growth of tumours derived from IFNγ-naïve YUMM2.1 cells nor enhanced the activity of α-PD-1 when both drugs were co-administered." (PMID 37752135, 2023). "Despite the recognition that IFNG has both pro-tumor and anti-tumor effects on cancer cells, these effects have not been quantified in great detail." (PMID 37182110, 2023). "We performed qRT-PCR on mRNA extracted from snap-frozen tumor tissue, measuring transcripts for IFNγ, to indicate response to ICI, and interferon regulatory factor 1 (IRF1), to indicate whether downstream IFNγ signaling is disrupted." (PMID 38130991, 2023). "To analyze the role of moDCs in anti-tumor immunity, we isolated the dLNs from mice immunized with T-MPs and found they became significantly larger, and the proportions of DCs and CD8+IFNγ+ T lymphocytes were significantly increased." (PMID 37089435, 2023). "Combination therapy with the tumor-targeted immunocytokine showed sustained NHS-IL12 localization in tumors compared to NHS-IL-12 monotherapy, which resulted in a sustained proinflammatory milieu with elevated IFNγ." (PMID 38260854, 2023). "Interferon-gamma secretion under antigen stimulation by splenocytes co-cultured with or without tumor cells was then quantified." (PMID 36138335, 2023).
tumor (continued). "Analysis of the tumor microenvironment (TME) in the combined-treatment group revealed an immune-inflamed TME characterized by increased infiltration of activated endogenous DCs and IFNγ+ CD8+ T cells, showing reduced signs of exhaustion." (PMID 37654492, 2023). "As expected, mice with tumor (but no recTLT-1) displayed higher proportions of activated (IFNγ-producing) CD8 T cells as compared with control mice (nontumor)." (PMID 36305874, 2023). "Our data suggest that PD-1high CAR-T cells are able to produce more IFNγ than PD-1low CAR-T cells, resulting in robust upregulation of ICAM-1 on target cancer cells, which then supports more stable T cell-tumor cell conjugation formations to improve T cell-mediated killing." (PMID 37388744, 2023). "The upregulation of pro-inflammatory cytokines can also lead to the production of IFNγ which can induce chemokines CXCL9 and CXCL10 to recruit NK cells, neutrophils, macrophages, and T cells to the tumor and stimulate acquired immunity for a tumor-specific response." (PMID 37588093, 2023). "Because antibodies to cytokines often exhibit neutralizing effects which might alter cellular communication within the tumor microenvironment, we also evaluated the impact of AN18 on downstream IFNγ signaling and ICI outcomes." (PMID 38130991, 2023). "IFNγ was the major contributor of the T cell effect in this setting, because its blockade by a specific antibody significantly both rescued the decline in TRP and protected tumor cells." (PMID 36812891, 2023). "IFNγ treatment resulted in a small increase in the average weight of FAK-wt tumours; however, this was not statistically significant." (PMID 36977556, 2023). "Chronic IFNγ pre-treatment did not affect tumour growth rates when mice were treated with control antibody." (PMID 37752135, 2023). "We found in the C24 model that while these tumors had high TGFβ like MEERvvR, treatment with VV alone did not increase IFNγ in the tumor." (PMID 37552475, 2023). "Additionally, their tumor‐infiltrating lymphocytes exhibited impaired tumor necrosis factor‐alpha (TNF‐α) and interferon‐gamma (IFN‐γ) production, with an elevated programmed cell death protein 1 (PD‐1) level." (PMID 37691307, 2023). "Additionally, at 2 months post cessation of combination therapy, all long-term survivors rejected the re-implantation of chronic IFNγ pre-treated YUMM2.1 cells, indicating the induction of anti-tumour immune memory." (PMID 37752135, 2023). "While data here clearly demonstrate that maximum human NOS2 expression is induced by IFNγ, IL1β, and TNFα, identical to that in murine tumor cells, human macrophages do not activate NOS2 with IFNγ or LPS." (PMID 37169743, 2023). "In this study, we provide evidence that IFNγ directly acts on TILs to restrict anti-tumor responses, independent of other checkpoints." (PMID 36658158, 2023). "Another example is the tumor inflammation signature (TIS) score, quantifying 18 specific T cell and interferon gamma (IFNγ) signaling pathways-related genes with key roles in coordinating and orchestrating an active but suppressive adaptive immune response in TIME." (PMID 37509366, 2023). "Furthermore, they found an increase in B cells and cytotoxic T cells to eliminate tumor cells by secreting cytokines such as TNF and IFNγ." (PMID 37408277, 2023). "In addition, we found increased frequency of IFNγ– and TNFα-producing CD8+ T cells in the tumor, indicative of their cytotoxic functionality." (PMID 37089449, 2023). "A single dose of intratumor with IL-12 mRNA delivered by LNP to mice could induce IFNγ and CD8+ T-cell dependent tumor regression." (PMID 37805495, 2023). "Rather than enhancing antitumor effects, blocking IFNγ in the context of anti-mCD19 CAR-T treatment abrogated the anti-tumor effects of CAR-T cells." (PMID 38052854, 2023). "Specifically, we examined interferon gamma production by lymph node cells restimulated with tumor antigens prepared by IR, UV, or F/T methods in tumor and non-tumor-bearing mice." (PMID 37444444, 2023).
tumor (continued). "In line with this, treatment of mice bearing the Arf1‐ablated tumor cells with anti‐IFNAR1 and anti‐IL‐1β antibodies had markedly reduced frequency of the TNF+IFNg+PD1+CD8+ T cells in tumors in comparison with those in tumors treated with the isotype control antibody." (PMID 37786300, 2023). "Importantly, recent studies have demonstrated that the adhesion between CAR-T cells and target cancer cells is directly regulated by IFNγ, which induces an upregulation of ICAM-1 on target tumor cells, promoting the formation of conjugations with CAR-T cells." (PMID 37388744, 2023). "IFNG, produced by Tex, also exhibited increased interaction with CXCL8/1 in the EMTPs of both stages, which is critical for CRC tumor invasion and deserves further analysis." (PMID 37940972, 2023). "Not surprisingly, APOL3-OE+RSL3+PD1 cohort tumor showed the largest IFNG expression and percent of IFNγ of CD8+ T cells compared to another 5 cohorts." (PMID 36923931, 2023). "Additionally, NHE1 protein blockade promoted an immunogenic tumor microenvironment by inducing the accumulation of CD8 T cells, enhancing interferon-gamma (IFN-γ) expression, and rendering animals sensitive to anti-PD-1 treatment." (PMID 37298344, 2023). "However, we used thymus aplastic nu/nu mice for the tumor model in our study, which indirectly suggested that the adaptive immunity can be missing for the anti-tumor effect of YB1 and IFNγ in our model." (PMID 38020179, 2023). "From a translational point of view, successful strategies to modulate IFNγ for tumour therapy are still lacking." (PMID 37056922, 2023). "The suppression or modification of interferon-gamma (IFN-γ) signalling, activation of the MAPK and Wnt/β-catenin pathways, a decreased T-cell response and tumour antigen production are a few often found pathways that inhibit the immunotherapy response leading to treatment resistance." (PMID 37569598, 2023). "As an additional test to determine whether the AN18 antibody was impacting IFNγ signaling within the tumor, we compared the ratio of IRF1:IFNγ transcripts, since IRF1 expression is in part dependent on the presence of IFNγ." (PMID 38130991, 2023). "A previous study based on different syngeneic tumor models has shown that CD8+ T cells co-expressing inhibitory receptors (IRs) are not dysfunctional, but rather highly express activation and effector-related marker genes such as IFNG, GZMB, MKI67, and ICOS." (PMID 37773254, 2023). "It should be mentioned that Phascolarctobacterium was also part of the 11-strain commensal consortium that was shown to robustly elicit interferon gamma-producing CD8 T cells in the intestine and improve the therapeutic efficacy of immunotherapy in tumor models." (PMID 37511376, 2023). "Increased IFNγ and IL-17 expression suggests enrichment of Th1/Th17 in BOXR1030 cells which could support a more potent anti-tumor response." (PMID 35507536, 2022). "A timeline of initial tumor growth, tumor reduction after IRE treatment, IFNγ expression and its stimulation of PD-1/PD-L1, activation/suppression of pattern recognition receptors, and the TGF-β pathway would help the field develop co-therapy targets and design improved clinical trials." (PMID 35372046, 2022). "The main mechanism of resistance to CTLA-4 blockade involves the lack of the genes for response to interferon gamma by tumor cells." (PMID 36556139, 2022). "In addition, the tumor-restricted clonotypes expressed lower effector markers (GZMB, PRF1, IFNG) compared with clonotypes shared with other tissues, indicating possible antigen-experience and exhaustion of TCR clonotypes in the TME." (PMID 36185254, 2022). "However, there are more Foxp3+Treg cells and less IFNγ+TH1 cells, but similar TH2 and TH17 cells in Piezo1-/- compared with WT bearing-tumor mice." (PMID 35993548, 2022). "On the other hand, IFNγ expression was undetectable irrespective of the tumor challenge in both IVpos and IVneg NK cell populations in the lungs." (PMID 36733396, 2022).